TNF (tumor necrosis factor)
Diseases named in the same sentence as TNF in open-access papers (continued):
Sharing a sentence is not in itself a finding about the gene and the disease.
heart failure (continued). "Visfatin increase in type-2 DM patients was related to heart failure and acute coronary syndromes; visfatin appears to mediate vascular endothelial inflammation by inducing the expression of adhesion molecules (VCAM-1 and ICAM-1) and pro-inflammatory cytokines such as IL-1β, IL-6, and TNF-α." (PMID 28590452, 2017). "We believe that the lack of statistically significant elevation in the levels of TNF-α in the anterior MI group, the group which had the poorest LV function, may have been due to the absence of severe clinical heart failure." (PMID 27805242, 2016). "Pro-inflammatory cytokines such as IL-1 and tumor necrosis factor alpha (TNFα), which are potent stimuli for the p38 MAPK pathway, are elevated in the infarcted heart and appear to be detrimental for post-MI myocardial remodeling and progression to heart failure." (PMID 27932994, 2016). "Therefore, it is not surprising that pharmacological inhibition of TNF-α activity improves myocardial function during heart failure." (PMID 26112171, 2015). "We therefore hypothesized that blocking the pro-apoptotic TNF-α pathway using pentoxifylline could prevent the deleterious effect of the lack of ET-1 in a model for heart failure." (PMID 24523936, 2014). "Anti-TNF-α therapies in patients with heart failure were not effective, a precise reason for this is unknown." (PMID 21949832, 2011). "In cardiac cells exposed to TNF-α, the inhibition of PDK4 expression by NF-κB is related to the shift towards increased glycolysis that is observed during cardiac pathological processes induced by pro-inflammatory stimuli, such as cardiac hypertrophy and heart failure." (PMID 21625432, 2011). "Moreover, TNF has been proven to have a negative inotropic effect and prolonged activation of TNF-alpha and its soluble receptors in heart failure patients, whether compensated or decompensated." (PMID 40660324, 2025). "However, many patients do not respond to TNF inhibitors and TNF blockers may even exacerbate inflammation in other diseases, e.g., heart failure or multiple sclerosis." (PMID 31555271, 2019). "However, clinical trials targeting TNF-α signalling in patients with heart failure have demonstrated neutral results in terms of death and hospitalization, suggesting that the involvement of chronic inflammation in heart failure is not as simple as expected." (PMID 29511093, 2018). "Thus, it is presumed that one mechanism underlying the beneficial effects of β-adrenergic blockade in heart failure may involve attenuation of TNF-α and IL-1β expression independent of iNOS and NO." (PMID 28674538, 2017). "Moreover, direct anti TNF-α therapies using specific antibodies did not ameliorate outcome in heart failure patients (e.g. infliximab: ATTACH trial, or eternecept: RENAISSANCE, RECOVER and RENEWAL trials), while PTX treatment can benefit patients in the absence of a reduction of TNF-α levels." (PMID 24523936, 2014). "TNF-a exerts both protective and injurious actions on the failing heart; as a result, anti-TNF therapy did not prove beneficial in heart failure patients." (PMID 26273700, 2015). "Future immunologic therapies will, no doubt, be based on emergent evidence that tumor necrosis factor (TNF-alpha) is an important humoral mediator of KATP channel remodeling in cardiomyocyte hypertrophy and heart failure." (PMID 21845191, 2011). "Pro-inflammatory cytokines (tumor necrosis factor alpha (TNF-α), interleukin-1β (IL-1β), IL-6, IL-8, IL-17, and IL-18), detected in the heart of patients with heart failure (but not in non-failing hearts), can induce compensatory cardiac hypertrophy and fibrosis in the setting of cardiac injury." (PMID 34440924, 2021). "The authors evaluated eighty-six subjects (33 patients with myocardial infarction, 33 patients with myocardial infarction and heart failure, and 20 controls) and found negative correlations between irisin and BMI, WHR, SBP, DBP, troponin-I, CK-MB, TNF-α, TC, TGs, and LDL-C." (PMID 32260434, 2020).
heart failure (continued). "Moreover, since the role of TNF-α and IL-6 SNPs in the pathogenesis of CHD has remained inconclusive, investigating patients with IHD and no heart failure might have given more conclusive results." (PMID 29849987, 2018). "Therefore, contraindications to the use of TNF-alpha inhibitors include an active infection (bacterial, fungal, herpes zoster, HBV, HCV, etc), active or latent TB, malignancy, demyelination disease, non-healed infection skin ulcers, or history of heart failure." (PMID 39280117, 2024).
malaria (599 papers, 2005 to 2026). Malaria is a serious and sometimes fatal disease caused by a parasite that commonly infects a certain type of mosquito which feeds on humans. "The modulation of TNF-α and IL-6 by potential therapeutic agents is of significant interest in developing effective treatments for malaria-associated complications." (PMID 40917784, 2025). "The − 1031CC genotype has been associated with increased malaria episodes, while the − 308AA genotype correlates with protection, suggesting that TNF-α expression levels influence disease susceptibility and severity." (PMID 40993672, 2025). "It has been observed that clinical or severe malaria is associated with increased levels of pro-inflammatory cytokines, including IL-1β, IL-6, IL-8, IL-10, IL-12, IL-13, IL-31, IL-33, and TNF-α." (PMID 39204168, 2024). "APAF-1 is linked to antifolate resistance and interleukin-1 receptor binding, while TNF-α is implicated in choline binding and infections like malaria and African trypanosomiasis." (PMID 39063550, 2024). "Elevated Ang 2 levels, which have been associated with endothelial injury in severe malaria, also correlate with severe infections and TNF-α secretion, highlighting its potential as a therapeutic target for managing disease complications." (PMID 39749215, 2024). "IL-10 plays an essential role in regulating inflammation during malaria and tissue damage caused by TNF." (PMID 39495782, 2024). "Although TNF, IL-6, and IL-12 are proinflammatory cytokines associated with severe malaria, their levels have been reported to be decreased in malaria and HBV coinfections." (PMID 36716305, 2023). "Given that immune response cells produce cytokines and malaria severity is associated with elevated concentrations of TNF-α, IL-6 and IL-10." (PMID 37628731, 2023). "Recent report shows that TNF-α plays dual role (which includes protective and pathogenic) in malaria physiopathology; as at higher levels, it promotes pathogenicity in cerebral malaria while it is protective against severe malaria at lower levels." (PMID 37215099, 2023). "Literature search outcomes included eight eligible articles in which TNF-α -308G >A polymorphism was determined in uncomplicated malaria (UM) and severe malaria (SM) of P. falciparum as represented in the case and control groups." (PMID 37910577, 2023). "This supports ethnicity as one of the dependent factors of the TNF-α -308G >A association with the clinical severity of malaria." (PMID 37910577, 2023). "Severe malaria is associated with several genes, including TNF-α gene polymorphisms.TNF-α is thought to be a critical factor in malaria pathogenesis, the control ofparasitemia, and increased susceptibility to severe malaria." (PMID 38774844, 2023). "Hereby, the principal cytokines associated with the severity of malaria by P. berghei infection were TNF-α, IFN-γ, and IL-12p70." (PMID 37492527, 2023). "The multifactorial pathogenesis of severe malaria is partly attributed to host genes, such as those encoding cytokines involved in complex inflammatory reactions, namely tumor necrosis factor-alpha (TNF-α)." (PMID 37910577, 2023). "In this study, a significant association was identified between symptomatic malaria and the TNF-α 308 GA mutation." (PMID 35291755, 2022). "There were significantly higher odds of TNF-α genotype GA being associated with symptomatic malaria as against asymptomatic malaria in both sites, Obom (p=0.027) and Asutsuare (p=0.027)." (PMID 35291755, 2022). "TNF-α 308 GA mutation increases the production of TNF, and reports indicate that overproduction of TNF leads to severe malaria, hence the manifestation of symptoms." (PMID 35291755, 2022). "TNF has long been implicated as one of the major contributors to poor pregnancy outcome in malaria-positive primigravid women and in other infections." (PMID 35312688, 2022).
malaria (continued). "In this study, we have found that IFNγ-producing CD4+ T cells and DN γδ T cells co-producing IFNγ and TNF are associated with parasite control among lifelong malaria-exposed Africans." (PMID 35922467, 2022). "It has been reported that profound levels of pro-inflammatory cytokines, such as TNF-α and IL-6 are associated with severe malaria." (PMID 35214662, 2022). "In Obom, marginal differences were observed in the distribution of the TNF-α 308 variants amongst the three malaria groups (p=0.05)." (PMID 35291755, 2022). "For example, a study conducted in Western Kenyan children showed that higher ratios of plasma IL-10 to TNF levels were strongly linked to protection against severe malaria anaemia." (PMID 35464430, 2022). "SNPs in the regulatory region of the TNF gene are associated with TNF production as well as the clinical outcomes of malaria in diverse populations." (PMID 35291755, 2022). "Studies in humans have suggested a role of IL-10 in regulating the pathogenic effects of TNF during malaria." (PMID 35464430, 2022). "infection was linked to higher TNF-α levels in patients with HAT than observed in patients with HAT or malaria mono-infections." (PMID 34893680, 2021). "A recent study found a correlation between P. falciparum-specific IL-10-positive T cells (IFN-γ- TNF-) and the risk of clinical malaria once infected." (PMID 34790829, 2021). "The response of γδ T cells to stimulation in vitro with malaria antigens is characterised by proliferation as well as production of cytokines including IFN-γ, IL-1β, and TNF-α which have been associated with protection against malaria disease." (PMID 34666102, 2021). "Some inflammatory response genes can be associated with malaria, like TNF-α, NOS2, Interferon-alpha/beta receptor alpha chain gene (IFNAR1), heme oxygenase 1 (HMOX1), TLRs, CD36, and CD40LG." (PMID 32599864, 2020). "In Gabonese patients, plasma levels of TNFα and nitric oxide were associated with parasite clearance and resolution of fever, although overproduction of either was associated with severe malaria." (PMID 31900030, 2020). "In endemic settings, higher frequencies of Vδ2 cells, as well as higher percentages of Vδ2 T cells that produce IFNγ and TNF upon malaria antigen stimulation, have been associated with protection against parasitemia." (PMID 33085728, 2020). "Studies have shown that increasing levels of TNF-α and IL-6 in malaria are associated with the cytoadherence of infected erythrocytes leading to the development of febrile disease." (PMID 33281757, 2020). "falciparum infected cases comprising of 103 uncomplicated cases and 211 severe malaria patients and genotyped for TNF-α (G-238A and G-308A) polymorphisms." (PMID 31409832, 2019). "Yet, TNF was also implicated as a causative factor in development of malaria-associated organ pathology." (PMID 31417551, 2019). "Severe malaria has been associated with low serum levels of IL-12 and low IL-10 to TNF- α serum concentration ratios in a few studies of childhood malaria in holoendemic areas." (PMID 34557294, 2019). "There are limited studies in the Indian population, especially, in the malaria endemic belts, for possible association between TNF-α polymorphisms (G-238A and G-308A) and SLE." (PMID 31409832, 2019). "Specifically, in human studies, increased placental TNF staining has been associated with increased risk of FGR in the context of malaria and lower birthweight in the context of schistosomiasis." (PMID 31188820, 2019). "We revisited genetic evidence provided by inflammatory response genes that have been repeatedly associated to malaria, namely TNF, NOS2, IFNAR1, HMOX1, TLRs, CD36, and CD40LG." (PMID 31417551, 2019). "Many studies from malaria endemic countries demonstrated an association of a high TNF-α and IL-10 plasma ratios in young children presenting with SMA44,46,75, which was also a distinguishing factor between our models of severe and moderate anaemia." (PMID 31831787, 2019).
malaria (continued). "TNF-α and IL-6 are both proinflammatory cytokines, which are associated with the severity of malaria." (PMID 31878288, 2019). "In our study, we have enrolled SLE patients and controls from malaria endemic areas of Eastern India and investigated the association of TNF-α promoter variants with SLE." (PMID 31409832, 2019). "The BOECs were shown to express known P. falciparum-IE adhesins associated with cerebral disease (ICAM-1/CD54 and EPCR/CD201), and levels of expression were altered in response to TNF-α, a cytokine associated with severe malaria." (PMID 30300360, 2018). "A low ratio of IL-10 to TNF in patients predicts more severe malaria, as do mutations in the IL-10 and TNF genes." (PMID 29866139, 2018). "This is supported by mechanistic studies of malaria-associated liver injury in mouse models, which demonstrate that heme-mediated oxidative damage is promoted by tumor necrosis factor (TNF) in a synergistic fashion." (PMID 29436349, 2018). "In humans, IFN-γ levels to schistosome egg and worm antigen has been found to decrease during pregnancy and high IL-10 levels as well as IFN-γ, TNF-α, IL-10 and IL-6 have been found to be associated with pregnancy associated malaria." (PMID 29970128, 2018). "Increased levels of IFN-γ, TNF-α, IL-12 and IL-10 are known to be associated with a reduced risk of malaria; however, those who become infected with malaria parasites have an elevated risk of symptomatic malaria." (PMID 29970128, 2018). "Elevated levels of IL-10 with low TNF-α have been associated with mild malaria, whilst recovery from malaria (parasite clearance) has been associated with reduced levels of IL-10." (PMID 29970128, 2018). "This has also been observed in clinical studies where a low ratio of plasma TGF-β and IL-10 to TNF-α was associated with severe malaria anemia in young children in malaria endemic communities in Africa." (PMID 29034874, 2017). "Inflammatory cytokines such as tumour necrosis factor- α (TNF-α), interleukin-1 (IL-1) and IL-6, have been described to correlate with severe malaria but the major role of TNF-α has been linked with parasite killing." (PMID 29034874, 2017). "An intronic SNP in LTA was associated with protection, and one SNP on the TNF promoter was associated with susceptibility to clinical malaria." (PMID 28243235, 2017). "TNF-α is one of the major macrophage-produced cytokines and is associated with the development of placental pathology during malaria." (PMID 29117241, 2017). "Although inflammatory responses, including interferon gamma (IFN-γ), IL-12, IL-1β, IL-2, and TNF-α, play important roles that facilitate parasite clearance, circulating high levels of these cytokines have been associated with malaria immunopathology." (PMID 28399920, 2017). "Aside the TNF association studies, the associations between malaria and polymorphisms in other genes located at HLA locus were also the focus of investigations." (PMID 26858717, 2016). "More recently plasma TNF level was determined by enzyme-linked immunosorbent assay in malaria naive donors and P. vivax infected donors indicating its concentration increases in infected samples up to about 1000 pg/ml." (PMID 27080559, 2016). "In patients with cerebral, severe malaria and mucocutaneous leishmaniasis, the TNF-α -308G/A polymorphism has been shown to be associated with the outcome and clinical course of the disease." (PMID 26858717, 2016). "Pantethine has been shown to prevent the perivascular inflammation and to protect mice against the cerebral syndrome associated with malaria; the protection was associated with a significantly lower level of circulating tumor necrosis factor (TNF)-α." (PMID 27900284, 2016). "We show that IL-10 produced by Tr1 cells protects against IFNγ-dependent, TNF-mediated tissue damage, but limited the control of parasites that cause malaria and VL." (PMID 26765224, 2016).